FOSL2 (FOS like 2, AP-1 transcription factor subunit)
Diseases named in the same sentence as FOSL2 in open-access papers (continued):
Sharing a sentence is not in itself a finding about the gene and the disease.
ovarian carcinoma (16 papers, 2008 to 2024). A malignant neoplasm originating from the surface ovarian epithelium. "A former study reported that FOSL2 is linked to ovarian cancer (OC) and inhibition of FOSL2 promotes the apoptosis of OC cells by mediating the formation of an inflammasome." (PMID 39010083, 2024). "Although it has been established that Fos-like antigen 2 (FOSL2) is linked to ovarian cancer (OC), its exact role in the development of OC remains unknown." (PMID 34773569, 2022). "FOSL2 expression in ovarian carcinoma and adjacent tissues was assessed using real-time fluorescent quantitative PCR and western blot." (PMID 34773569, 2022). "At the core of the molecular mechanism of these changes is that lncRNA UCA1 negatively affects the expression of miR-143, which in turn is a modulator of FOS-like 2, AP-1 transcription factor subunit (FOSL2) expression in ovarian cancer cells." (PMID 36139487, 2022). "High expression of FOSL2 has been confirmed in several types of cancer, including colon cancer, breast cancer, ovarian cancer, liver cancer, and osteosarcoma." (PMID 36139487, 2022). "FOSL2 was found to be aberrantly expressed in non-small-cell lung cancer, ovarian cancer, liver cancer, and other malignant tumors and is involved in the growth and metastasis of tumor cells as a prooncogene." (PMID 35003395, 2021). "The lncRNA UCA1 promotes ovarian cancer cell chemoresistance by sponging miR-143 to activate FOSL2 Signaling Pathway." (PMID 31747939, 2019). "This article aims to investigate the role of FOSL2 in ovarian cancer development." (PMID 34773569, 2022). "Literature reported dysregulation of miR-591 confer paclitaxel resistance to ovarian cancer, and circ_0091581 could promote the progression of hepatocellular carcinoma through miR-591/FOSL2 Axis." (PMID 35111412, 2022). "Abnormal expression of FOSL2 was also found in osteosarcoma, colon cancer and ovarian carcinomas." (PMID 34041036, 2021). "For example, by binding to the 3′-UTR of FOS-like 2 (FOSL2), miR-143 can negatively regulate FOSL2 expression, suggesting that the UCA1/miR-143 axis may have potential therapeutic value for the treatment of cisplatin resistance in ovarian cancer patients." (PMID 36717926, 2023). "Via binding to the 3′-UTRs of FOS-like 2 (FOSL2), miR-143 can negatively regulate FOSL2 expression, suggesting that the UCA1/miR-143 axis may have potential therapeutic value for the treatment of cisplatin resistance in ovarian cancer patients." (PMID 34512721, 2021).
hepatocellular carcinoma (13 papers, 2020 to 2024). A malignant tumor that arises from hepatocytes. "Previous studies have shown that FOSL2 promotes the proliferation, migration, and invasion of various cancers, including non-small-cell lung cancer, hepatocellular carcinoma, and CRC." (PMID 34782005, 2021). "In hepatocellular carcinoma, FOSL2 is a target gene of MiR-133a, which promotes the proliferation and metastasis of liver cancer cells through the TGF-β /Smad3 signaling pathway." (PMID 33712565, 2021). "Previous studies showed that FOSL2 expression promotes proliferation, migration, and invasion of cancers, including osteosarcoma, hepatocellular carcinoma, and colon cancer." (PMID 33221767, 2020). "Previous study found that miR-591 could regulate hepatocellular carcinoma apoptosis through regulating FOSL2 expression." (PMID 33658057, 2021). "MiR-133a could suppress hepatocellular carcinoma (HCC) by targeting Fos-related antigen 2 (FOSL2) and inactivating TGF-β/Smad3 signaling pathway." (PMID 33391416, 2021).
systemic sclerosis (12 papers, 2014 to 2026). A chronic disorder, possibly autoimmune, marked by excessive production of collagen which results in hardening and thickening of body tissues. "Fosl-2 has been shown to regulate profibrotic effects of TGF-β in dermal fibroblasts of patients with systemic sclerosis and in mouse models of scleroderma, but its role in the regulation of autophagy has not been acknowledged until now." (PMID 33668422, 2021). "For example, FOSL2 is overexpressed in systemic sclerosis (SSc) and acts as a novel downstream mediator of the profibrotic cytokine TGF-β." (PMID 25375657, 2014).
non-small cell lung carcinoma (11 papers, 2014 to 2025). A group of at least three distinct histological types of lung cancer, including non-small cell squamous cell carcinoma, adenocarcinoma, and large cell carcinoma. "It has been shown that FOSL2 positively regulates TGF-β1 signaling in non-small cell lung cancer." (PMID 37334370, 2023). "In addition, FOSL2 could regulate the epithelial-mesenchymal transitions (EMT), invasion, and migration by transcriptional regulation of SNAI2 in non-small cell lung cancer." (PMID 39010083, 2024).
osteosarcoma (11 papers, 2018 to 2025). A usually aggressive malignant bone-forming mesenchymal neoplasm, predominantly affecting adolescents and young adults. "FOSL2 is expressed in stromal cells of human chondroblastic and osteoblastic osteosarcomas, and the deficiency of FOSL2 induces a differentiation defect in osteoblasts both in vivo and in vitro experiments." (PMID 36092920, 2022). "Meanwhile, miR - 143 - 3p inhibits osteosarcoma cell proliferation and metastasis while promoting apoptosis by targeting FOS - like antigen 2 (FOSL2)." (PMID 40837012, 2025). "illustrated that knockdown of LINC00313 suppresses metastasis and tumorigenesis in osteosarcoma via modulating miR-342-3p/FOSL2 axis." (PMID 34102610, 2021). "In the study of osteosarcoma, miR-143 directly and negatively targets FOSL2 to inhibit osteosarcoma cell proliferation and metastasis and promote apoptosis." (PMID 34946965, 2021). "The lncRNA LINC00313 acts as a sponge for miR-342–3p, regulating FOSL2 levels and inhibiting autophagy in human osteosarcoma cells, ultimately suppressing osteosarcoma cell metastasis." (PMID 34095215, 2021). "Our data further showed that circ0003998 could sponge with miR-143-3p to increase the expression of FOSL2 and thereby promoted the EMT in HCC and it has been consistently showed that FOSL2 is the target gene of miR-143-3p in osteosarcoma in previous study." (PMID 32552766, 2020). "In vitro assays have identified that miR-143 regulates proliferation, apoptosis, and migration of osteosarcoma cells via targeting multiple key molecules, such as MAPK7 and FOS-Like antigen 2 (FOSL2) 18-20." (PMID 33850470, 2021).
colon carcinoma (10 papers, 2019 to 2025). "Upregulation of FOSL2 at 2p22 is associated with colon cancer, and increased levels of FNDC4 transcripts are associated with increased inflammation in mouse models and in IBD patients." (PMID 34178034, 2021). "In order to study the association between miR-597-5p and FOSL2 in human colon cancer, we checked the expression of miR-597-5p and FOSL2 in an independent cohort of 21 CRC patients." (PMID 31245295, 2019). "The effect of expression of FOSL2 and colon cancer cells possessing wild-type KRAS in terms of sensitivity is yet to be studied." (PMID 31245295, 2019). "Collectively, these observations are a confirmation that miR-597-5p targets FOSL2 in normal colonic epithelial cells and that its down regulation in tumorigenic colon cells results in the induction of FOSL2 expression in colon cancer cells." (PMID 31245295, 2019). "Another study unveiled a critical role of FOSL2 in promoting metastasis in colon cancer." (PMID 39010083, 2024). "However, to the best of our knowledge, this study is a first that shows differential regulation of FOSL2 by miR-597-5p in normal and tumorigenic colon cancer cells." (PMID 31245295, 2019). "Given that our current experiments and earlier results indicated that miR-597-5p and FOSL2 have an inverse effect on EMT markers and in vitro motility in LoVo cells, we put forth a hypothesis that human colon cancer may have suppressed levels of miR-597-5p leading to FOSL2 upregulation." (PMID 31245295, 2019). "As migration and invasion of epithelial cells of the human colon (FHC cell line) in vitro was influenced by changing levels of FOSL2, we can hypothesize that regardless of the KRAS (wild-type or mutant), the sensitivity of colon cancer cells is influenced by the expression of FOSL2." (PMID 31245295, 2019). "We next assessed whether FOSL2 is a true target of miR-597-5p in the context of colon cancer." (PMID 31245295, 2019). "We further sought to understand the molecular mechanisms of certain critical DETFs, FOSL2 and KLF6, in FR colon cancer cells." (PMID 40082673, 2025). "FOSL2 also regulates the TGF-β signaling pathway, thereby affecting the migration of colon cancer cells." (PMID 33739370, 2021). "As FOSL2 favors a mesenchymal phenotype, it is not unexpected that the expression of this factor can influence the sensitivity of colon cancer cells to PTX." (PMID 31245295, 2019). "Moreover, relatively high coexpression scores were also observed for FOSL2/KLF6, FOSL2/RUNX2 and GRHL2/FOXA1, suggesting that the DETFs related to H3K23su DERs might work together and be responsible for 5-FU resistance in HCT15 colon cancer cells." (PMID 40082673, 2025).
colorectal cancer (9 papers, 2008 to 2025). A primary or metastatic malignant neoplasm that affects the colon or rectum. "Our previous work had shown that FOS-like antigen 2 (FOSL2) is regulated by miR-143-5p in colorectal cancer (CRC)." (PMID 31245295, 2019). "Based on TCGA data, there was a positive correlation between FOSL2 and KRAS expression in PDAC, colorectal carcinomas, and lung adenocarcinomas." (PMID 37380804, 2023).
lung carcinoma (9 papers, 2012 to 2025). "In order to further validate the association of the TGFβ‐FOSL2 axis in MP‐patterned malignancy, we first knocked down FOSL2 or inhibited TGFβ in lung cancer cells co‐cultured with M2‐like macrophages." (PMID 39899538, 2025). "FOSL2 activation in macrophages promotes the polarization of M2 macrophages and is related to lung cancer development and migration." (PMID 38600248, 2024). "Furthermore, high expression of β-catenin and Fosl2 and low expression of Arid5a were found in a transcriptome analysis of lung cancer cases and were correlated with poor prognosis." (PMID 35126382, 2021). "Indeed, our results suggest that the core transcriptional regulatory circuitry of A549 lung cancer cells is centered on FOSL2 and FOXA2." (PMID 27739523, 2016). "Interestingly, both FOXA2 and FOSL2 are suspected to play major role in lung cancer progression." (PMID 27739523, 2016). "β-catenin also mediates the activation of FOS-like antigen 2 (FOSL2) and repression of the AT-rich interaction domain 5A (ARID5A) driving TAMs to switch from M1-like to M2-like in lung cancer." (PMID 37759870, 2023).
melanoma (8 papers, 2013 to 2025). A malignant, usually aggressive tumor composed of atypical, neoplastic melanocytes. "For example, in melanoma cells strongly upregulated miR-3689f, miR-6840-5p, miR-4652-5p, miR-4706, and miR-4435 share the target FOSL2, a transcription factor that dimerizes with JUN and binds to AP-1 sites." (PMID 34073664, 2021). "Furthermore, we identified POU2F2, IRF1, and FOSL2 as the most highly correlated TFs with CD274 expression in melanoma across all five datasets." (PMID 34503064, 2021). "ChIP-seq in melanoma cells revealed that CHD4 occupied an intronic regulatory element in PADI1 immediately adjacent to sites occupied by transcription factors CTCF and FOSL2 (AP1)." (PMID 33741961, 2021).
pulmonary hypertension (8 papers, 2018 to 2024). Increased pressure within the pulmonary circulation due to lung or heart disorder. "Studies have shown that Fosl2 is a novel mediator of cell proliferation, differentiation, and transformation in the fibrotic pathophysiology of certain diseases, such as scleroderma and pulmonary hypertension." (PMID 29929510, 2018). "FOSL2, also known as Fra-2, is a critical gene within the Fos family that acts as a novel mediator of cell proliferation, differentiation, and transformation in the fibrotic pathophysiology of certain conditions, including scleroderma and pulmonary hypertension." (PMID 38474264, 2024).
Sepsis (4 papers, 2021 to 2025). Sepsis is defined as life-threatening organ dysfunction caused by a dysregulated host response to infection. "FOSL1 and FOSL2 have been shown to promote apoptosis in renal cells of mice with sepsis-associated nephritis and in podocytes of mice with nephrotic syndrome." (PMID 41155564, 2025). "MiR-30e suppresses apoptosis and promotes hepatocyte proliferation in cecal ligation and puncture-induced sepsis by regulating the JAK/STAT signaling mediated by FOSL2." (PMID 39067063, 2025). "Both JUNB and FOSL2 were identified as sepsis MR candidates common to RA and MS." (PMID 34680414, 2021). "Analysis of transcription factor expression for the DEGs above revealed that Fosl2 and Jdp2, components of the AP‐1 transcription factor complex, were specifically and highly expressed in Hep_Cd9, further supporting its proinflammatory function in response to sepsis." (PMID 37808269, 2023).
type 2 diabetes (4 papers, 2016 to 2023). "A study on the involvement of FOSL2 in type 2 diabetes found that the epigenetic downregulation of FOSL2 mRNA and protein expression levels by DNA hypermethylation may induce the occurrence of type 2 diabetes in patients." (PMID 34295261, 2021).
viral infection (4 papers, 2020 to 2025). "The 4T1 cell-CM significantly upregulated the expression of Fosl2 in macrophages, a change that was effectively reversed by viral infection." (PMID 40547518, 2025).
adult T-cell leukaemia (3 papers, 2015 to 2022). "A previous report has shown that FOSL2 is constitutively expressed in adult T-cell leukemia (ATL), up-regulates CCR4 expression, and promotes ATL cell growth, together with JunD proto-oncogene, AP-1 transcription factor subunit (JUND)." (PMID 33385611, 2020).
Autoimmunity (3 papers, 2021 to 2024). The occurrence of an immune reaction against the organism's own cells or tissues. "Recent studies have shown that FOSL2 represses Treg development and controls autoimmunity and can also control autoreactive B cells in patients with Systemic lupus erythematosus (SLE)." (PMID 34500467, 2021). "In a Fosl2 overexpressing mice model, AP1 has been shown to promote systemic autoimmunity and multiple organ inflammation by repressing regulatory T cells development." (PMID 38835762, 2024).
bladder cancer (3 papers, 2021 to 2023). "In this retrospective study, we have focused on the prognostic value of CEP63, FOSL2 and PAQR6 in bladder cancer." (PMID 34041036, 2021). "UCA1/miRNA204-5p/cAMP responsive element binding protein-1 (CREB1) axis, UCA1/miRNA-143/Fos-like antigen 2 (FOSL2) axis, and UCA1/miRNA-196a-5p/CREB axis were involved in enhancing the chemoresistance of colorectal, ovarian, and bladder cancers." (PMID 34544452, 2021).
glioblastoma (3 papers, 2021 to 2024). The most malignant astrocytic tumor (WHO grade IV). "In connection to previously reported glioblastoma mesenchymal signature transcription factors, SFRP2 increased and correlated with the expression of CEBPB, RUNX1, and FOSL2 in TCGA glioblastomas." (PMID 34021259, 2021). "Regarding previously reported glioblastoma mesenchymal signature transcription factors, SOX2 as opposed to SFRP2, decreased CEBPB and FOSL2 levels consistent with their negative correlation to SOX2 in TCGA glioblastomas." (PMID 34021259, 2021).
lung adenocarcinoma (3 papers, 2021 to 2023). A carcinoma that arises from the lung and is characterized by the presence of malignant glandular epithelial cells. "β-Catenin regulates the transition from M1 to M2 macrophages by activating FOSL2, leading to poor prognosis in patients with lung adenocarcinoma." (PMID 37954130, 2023). "A novel four-gene signature (INPP5B, FOSL2, CDCA3, RASAL2) was established to predict relapse-related survival outcomes in patients with early lung adenocarcinoma after surgery." (PMID 34430085, 2021).
pancreatic cancer (3 papers, 2023 to 2024). "By blocking CCL28 expression upon FOSL2 overexpression, we successfully suppressed Treg cell infiltration and tumour growth, providing insights into the role of FOSL2 in shaping the immune microenvironment of pancreatic cancer." (PMID 37380804, 2023). "In the present study, we identified CCL28 as a key mediator linking FOSL2 and the pancreatic tumour microenvironment." (PMID 37380804, 2023). "Importantly, our study demonstrated that CCL28 blockade upon FOSL2 overexpression exerted a potent anti-tumour effect by suppressing Treg cell infiltration and might serve as a potential therapeutic target for pancreatic cancer." (PMID 37380804, 2023). "Mechanistically, we found that FOSL2 bound to the upstream region of CCL28 to activate its expression, leading to the recruitment of Treg cells and highlighting the importance of the FOSL2-CCL28-Treg axis in pancreatic cancer." (PMID 37380804, 2023).
autoimmune disease (2 papers, 2022 to 2024). A disorder resulting from loss of function or tissue destruction of an organ or multiple organs, arising from humoral or cellular immune responses of the individual to their own tissue constituents. "We identified hundreds of autoimmune disease-associated SNPs within the genomic-binding sites of FOSL1, FOSL2 and BATF." (PMID 35511484, 2022). "Our study further reveals that the genomic binding sites of FOSL1, FOSL2 and BATF harbour hundreds of autoimmune disease-linked SNPs." (PMID 35511484, 2022).
breast tumor (2 papers, 2021 to 2024). "Collectively, these data indicate that FOSL2 in stromal fibroblasts potentially affects angiogenesis in breast tumors." (PMID 33754039, 2021). "In contrast, the proliferation and invasion abilities of breast tumor cells were increased by CM from FOSL2-overexpressing NFs." (PMID 33754039, 2021). "FOSL2 was highly expressed in breast tumor tissues than in adjacent normal tissues." (PMID 39010083, 2024). "Previous studies revealed that FOSL2 was abundantly expressed in breast tumor cells." (PMID 33754039, 2021). "The elucidation of reciprocal interactions of breast CAFs with endothelial cells may inspire the development of conceptually novel targeted therapeutics with the aim of thwarting the FOSL2/Wnt5a axis of breast tumor angiogenesis." (PMID 33754039, 2021).